CCL18 (C-C motif chemokine ligand 18)
Diseases named in the same sentence as CCL18 in open-access papers (continued):
Sharing a sentence is not in itself a finding about the gene and the disease.
breast tumor (8 papers, 2017 to 2025). "CCL18 is produced abundantly by breast tumor-associated macrophages (TAMs), and its expression is also associated with tumor metastasis." (PMID 36805828, 2023). "These immune cell association patterns suggest that both CCL18 and EGF are engaged in complex immune regulatory processes within breast tumors." (PMID 40692603, 2025). "It has been well established that PITPNM3 is a functional receptor of CCL18 in breast tumor cells and T lymphocytes." (PMID 36418470, 2023). "Tumor-infiltrating naive CD4+ T cells are recruited to breast tumors by CCL18 and converted to functional immunosuppressive Tregs." (PMID 36418470, 2023). "The clinical data displayed opposite expression patterns of CCL18 and IL-32θ mRNA in macrophage-infiltrated breast tumor tissues compared with those in the other tissues tested." (PMID 31126309, 2019). "Based on expression data, CCL18 is an attractive candidate chemokine for recruiting naive CD4+ T cells to breast tumors." (PMID 28290464, 2017). "Here we show that the TAM-produced chemokine CCL18 recruits circulating naive CD4+ T cells to breast tumors by binding their PITPNM3 receptor." (PMID 28290464, 2017). "Unexpectedly, CCL18 treatment didn’t enhance the survival of breast tumor cells under chemotherapy." (PMID 36418470, 2023). "Furthermore, CCL18-PITPNM3 signaling also plays other roles in breast tumor progression, such as immunosuppression and angiogenesis." (PMID 36418470, 2023). "The analysis revealed significantly reduced promoter methylation levels for both CCL18 and EGF in primary breast tumor samples relative to normal breast tissues (normal n = 97; tumor n = 793; p < 0.05)." (PMID 40692603, 2025). "During the investigation of the IL-32θ-regulated signaling upstream factors, CCL18 was considered as a potential activator due to its presence in the THP-1 macrophage CM, and the inverse expression between IL-32θ and CCL18 in breast tumor tissues infiltrated with CD206+ macrophages." (PMID 31126309, 2019). "It is worth noting that neutralizing CCL18 has no appreciable effect on tumor growth in NOD/scid mice bearing orthotopic breast tumors, which are not “humanized”, i.e., reconstituted with human immune cells." (PMID 28290464, 2017). "In cancer cells, CCL18–PITPNM3 enhances migration and EMT, but does not enhance the survival of breast tumor cells under chemotherapy." (PMID 36418470, 2023).
Gaucher disease (8 papers, 2015 to 2024). Gaucher disease (GD) is a lysosomal storage disorder encompassing three main forms (types 1, 2 and 3), a fetal form and a variant with cardiac involvement (Gaucher disease - ophthalmoplegia - cardiovascular calcification or Gaucher-like disease). "Analysis of Gaucher disease biomarkers in N-GD3 patients after 14 months of the imiglucerase supply shortage showed more pronounced increases in CCL18/PARC concentration than in chitotriosidase activity." (PMID 25205209, 2015). "CCL18 has previously been shown to be elevated in serum/plasma from individuals with lysosomal diseases, specifically Gaucher disease, Niemann-Pick disease type B or acid sphingomyelinase deficiency, GM1 gangliosidosis, NPC and possibly lysosomal acid lipase deficiency." (PMID 36721240, 2023). "Systemic analysis included genotype, plasmatic biomarkers, [ferritin, chemokine ligand 18 (CCL18) and chitotriosidase (ChT)] and severity scoring systems results [“Gaucher Disease Severity Score Index Type I" (GauSSI-I) and “Gaucher disease severity scoring system” (GD-DS3)]." (PMID 34871300, 2021). "The reason for the link between CCL18 and all-cause mortality is at present not clear, but high expression of CCL18 has been associated with several medical conditions involving cancer, immunological and inflammatory diseases, and Gaucher disease." (PMID 38596196, 2024). "Moreover, given that studies are increasingly recognizing the role of immune dysregulation and inflammation driven by chemokines such as CCL18 in the pathogenesis of Gaucher disease, CCR1 modulation could also be relevant for the Gaucher patients developing PD." (PMID 38673922, 2024). "In the same study, CCL18/PARC showed no significant changes during the ERT shortage period, and the authors concluded that probably this biomarker of Gaucher disease is less sensitive than chitotriosidase." (PMID 25205209, 2015).
lung adenocarcinoma (8 papers, 2012 to 2024). A carcinoma that arises from the lung and is characterized by the presence of malignant glandular epithelial cells. "chemokine ligand 18 (CCL18) is associated with the invasion, migration, metastasis and poor prognosis of lung adenocarcinoma (LUAD)." (PMID 34120429, 2021). "Patients suffering from squamous carcinoma disclosed a slightly higher mean CCL18 serum level compared with patients suffering from lung adenocarcinoma, however, this was of minor significance." (PMID 22848587, 2012). "In patients with adenocarcinoma of the lung we found a mean survival time of 388 days in the group with the highest CCL18 level." (PMID 22848587, 2012). "CCL18 predict also the survival time in patients with adenocarcinoma of the lung." (PMID 22848587, 2012). "In contrast, in lung adenocarcinoma cells, hypoxia reduces CCL18 expression, but the observed effect was not statistically significant." (PMID 35955670, 2022).
oral cancer (8 papers, 2016 to 2023). "CCL18 overexpression has also been revealed to be associated with the proliferation, invasiveness, and angiogenesis of oral cancer cells, as well as the TNM stage." (PMID 33795528, 2021). "The identification of the mechanisms underlying CCL18-mediated promotion of OSCC progression could highlight potential therapeutic targets for treating oral cancer." (PMID 32641093, 2020). "A recent study has shown that stimulation of oral cancer cells with CCL18 led to the activation of STAT3 signaling pathway that plays an important role in the growth and EMT process in cancer." (PMID 36217054, 2023). "The LINC00319/miR-199a-5p/FZD4 axis, as a ceRNA network, is an important signaling pathway through which CCL18 regulates the proliferation, invasiveness, and angiogenesis of oral cancer cells." (PMID 32948745, 2020). "Our previous work has shown that CCL18 promotes hyperplasia and invasiveness of oral cancer cells; however, the cognate receptors of CCL18 involved in the pathogenesis of oral squamous cell carcinoma (OSCC) have not yet been identified." (PMID 32641093, 2020). "LY294002, a pan-PI3K inhibitor, was used to abolish CCL18-induced Akt activation and observe the effects on oral cancer cell growth and invasion." (PMID 26919103, 2016). "To further confirm the increase in CCL18 expression in oral cancers, we examined the mRNA and protein levels of CCL18 in 3 OSCC cell lines (HSC-6, CAL33, and CAL27) and in normal oral keratinocytes (NOK)." (PMID 26919103, 2016). "Collectively, these observations indicate that CCL18 accelerates oral cancer cell growth in vitro and in vivo." (PMID 26919103, 2016). "To neutralize CCL18 function in oral cancer cells, we used both a CCL18 antibody as well as CCL18 siRNA." (PMID 26919103, 2016). "This could be explained by the important role of CCL18 in oral cancer where it promotes hyperplasia and metastasis by JAK2/STAT3 signaling pathways." (PMID 34025655, 2021). "Importantly, the expression of miR-199a-5p and FZD4 were found to be mediated by CCL18, and miR-199a-5p mimics inhibited the CCL18-promoting effects in oral cancer cells." (PMID 32948745, 2020). "Our previous research reported that the abundant expression of CCL18 examined in OSCC could promote the growth and metastasis of cancer cells, and was therefore associated with the TNM stage of oral cancer patients." (PMID 32948745, 2020). "Our previous work showed that CCL18, that was predominantly secreted by oral cancer cells, could promote the malignant progression of OSCC." (PMID 32641093, 2020). "CCL18 expression was primarily located in the cytoplasm and cell membrane of oral cancer cells." (PMID 26919103, 2016). "Besides, CCL18 could facilitate the proliferation of oral cancer cells through the JAK2/STAT3 signaling pathway." (PMID 36850011, 2023). "Therefore, in oral cancer, CCL18 likely acts in an autocrine manner." (PMID 26919103, 2016). "Therefore, we assessed whether Akt activation was involved in CCL18 autocrine signaling in oral cancer." (PMID 26919103, 2016). "CCL1 and CCL18 may either play a role in CCR8+ Treg migration to the malignant zone of oral cancer or they might induce its expression directly, thus, we measure chemotaxis and CCR8 induction in response to recombinant chemokines CCL1 and CCL18." (PMID 34025655, 2021). "Our previous study revealed that CCL18 was overexpressed in OSCC and could enhance the growth and metastasis of oral cancer by activating the PI3K/AKT signaling pathway." (PMID 32948745, 2020). "Overall, our data suggest that the secretome from oral cancer induces CCR8 and promotes a Th2 lineage in the T cell repertoire by several mechanisms; rapid membrane VitD mediated PGE2 production, accumulation of Vitamin D in cancer areas and increasing CCL18 levels." (PMID 34025655, 2021).
rheumatoid arthritis (8 papers, 2006 to 2023). A chronic, systemic autoimmune disorder characterized by inflammation in the synovial membranes and articular surfaces. "It should be noted that in our study the mean values of CCL18 in IIMs-ILD patients are considerably higher than those reported in Rheumatoid Arthritis and SSc and closer to those reported in active hypersensitivity pneumonia." (PMID 37238199, 2023). "Rheumatoid arthritis (RA) is one of these conditions, in which abundant CCL18 production is present." (PMID 16984635, 2006). "In order to identify whether other truncated forms of CCL18 exist during inflammation we isolated CCL18 from the synovial fluid of rheumatoid arthritis (RA) patients using SELDI-TOF MS." (PMID 23874339, 2013). "For example in synovial fluids from septic arthritis and rheumatoid arthritis patients levels of 140 ng/ml and 190 ng/ml CCL18 were determined, respectively, whereas in the non-inflammatory conditions of osteoarthritis and crystal induced arthritis, the levels of CCL18 are 34 and 38 ng/ml." (PMID 23951310, 2013).
squamous cell carcinoma (8 papers, 2012 to 2024). A carcinoma arising from squamous epithelial cells. "It has also been shown that CCL18 can increase the expression of stem cell markers in the cells of tumors such as oral squamous cell carcinoma and squamous cell carcinoma of the head and neck." (PMID 33114763, 2020). "Interestingly, the expression of CCL18 was mainly observed in the basal stratified squamous epithelium in non-malignant samples, whereas its expression in cancer samples was within the squamous cell carcinoma." (PMID 34025655, 2021). "Furthermore, CCL18 promoted cell growth and cell motility in squamous cell carcinoma of the head and neck." (PMID 34354751, 2021). "However, although T1 stages in squamous carcinoma or mixed NSCLC are also R0 resected we found a correlation between CCL18 serum level and survival time only in patients with adenocarcinoma but not in squamous carcinoma or mixed NSCLC." (PMID 22848587, 2012). "The activation of NF-κB by CCL18 also increases the expression of metadherin (MTDH), which leads to the EMT of the cells of the squamous cell carcinoma of the head and neck." (PMID 33114763, 2020). "It is of interest that in sera from patients with squamous carcinoma, CCL18 levels are also increased; however, theses CCL18 levels have no impact on the survival time of these patients." (PMID 38334630, 2024).
chronic obstructive pulmonary disease (7 papers, 2012 to 2024). A chronic and progressive lung disorder characterized by the loss of elasticity of the bronchial tree and the air sacs, destruction of the air sacs wall, thickening of the bronchial wall, and mucous accumulation in the bronchial tree. "Recently, Sin and co-workers demonstrated that CCL18 is increased in chronic obstructive pulmonary disease (COPD) and that this increase is linked with increased total mortality in COPD." (PMID 22848587, 2012). "This study aimed to investigate the association between serum concentrations of chemokine (C–C Motif) ligand 18 (CCL-18) and interleukin 23 (IL-23) and clinical parameters of chronic obstructive pulmonary disease (COPD)." (PMID 33082377, 2020). "Notably, studies have revealed a significant increase in CCL18 and CX3CL1 levels in patients with conditions such as chronic obstructive pulmonary disease (COPD) and chronic cough with phlegm (CCP) when compared to healthy individuals." (PMID 37944262, 2023).
lymph node metastasis (7 papers, 2016 to 2024). "Clinical significance analyses revealed that serum CCL18 level was closely linked with primary tumor site, tumor classification, clinical stage, lymph node metastasis and recurrence in patients with LSCC." (PMID 31839826, 2019). "Univariate Cox regression analyses initially indicated that primary tumor site, T staging, clinical stage, lymph node metastasis and serum CCL18 level were significantly associated with the overall survival in patients with LSCC (All P < 0.05)." (PMID 31839826, 2019). "In NSCLC tissues, a strong expression of CCL18 is correlated with lymph node metastasis, distant metastasis and poor prognosis." (PMID 35159163, 2022). "CCL18 levels were found to be significantly correlated with tumour classification, clinical stage, lymph node metastasis and histological grade in SCCHN patients." (PMID 30768878, 2019). "Our previous study showed that CCL18 was highly expressed in tumor tissues and the serum and was also closely associated with lymph node metastasis and a poor prognosis in NSCLC patients, suggesting that CCL18 plays an important role in NSCLC progression, especially in tumor metastasis." (PMID 36217054, 2023). "Serum CCL18 level was positively associated with primary tumor site (Glottic vs. Others; P < 0.001), tumor classification (T1+T2 vs. T3+T4; P < 0.001), clinical stage (I+II vs. III+IV; P < 0.001) and lymph node metastasis (N0 vs. N+; P < 0.001)." (PMID 31839826, 2019). "Furthermore, serum CCL18 levels correlated with tumour classification, clinical stage, lymph node metastasis and histological grade significantly." (PMID 30768878, 2019). "Moreover, serum CCL18 level was significantly associated with primary tumor site (Glottic vs Others), T classification (T1+T2 vs T3+T4), clinical stage (I+II vs III+IV) and lymph node metastasis (N0 vs N+)." (PMID 31839826, 2019). "Statistical analysis confirmed that CCL18 overexpression was only correlated with the TNM stage, whereas VCAM-1 overexpression was correlated with the TNM stage, lymph node metastasis, and perineural invasion." (PMID 29670110, 2018). "Eight clinical parameters including age, gender, primary tumor site, histopathological grade, T staging, presence or absence of lymph node metastasis, clinical staging and serum CCL18 level were initially enrolled in univariate analysis." (PMID 31839826, 2019). "Moreover, the univariate and multivariate analysis demonstrated that the TNM stage, lymph node metastasis, VCAM-1 expression, and CCL18 expression were independent prognostic factors." (PMID 29670110, 2018).
non-small cell lung carcinoma (7 papers, 2012 to 2022). A group of at least three distinct histological types of lung cancer, including non-small cell squamous cell carcinoma, adenocarcinoma, and large cell carcinoma. "In non-small cell lung cancer, a greater infiltration of CCL18-producing cells is associated with a better prognosis, although the level of this chemokine in the plasma of patients with this type of cancer is associated with a worse prognosis." (PMID 33114763, 2020). "We already demonstrated that CCL18 is highly elevated in sera of patients with non small cell lung cancer and correlates with tumor stage and overall survival in the subgroup of adenocarcinoma." (PMID 23349697, 2013). "Our study investigated for the first time the serum level of CCL18 in patients with non-small-cell lung cancer." (PMID 22848587, 2012). "In cancer tumors, CCL18 is mainly produced and secreted into the tumor microenvironment by tumor-associated macrophages (TAM) and in much smaller amounts by GBM cancer cells, as shown in non-small cell lung cancer cells and melanoma cells." (PMID 35955670, 2022). "In non-small cell lung cancer cells, CCL18 reduces proliferation." (PMID 33114763, 2020). "CCL18 is a marker of alternatively activated macrophages and has therefore an important impact in the orchestra of the “chemokine cross-talk” in the microenvironment of non-small-cell lung cancer." (PMID 22848587, 2012).
asthma (6 papers, 2020 to 2025). "CCL18 is the most highly expressed chemokines by antigen-presenting cells (APCs) in AD and asthma subjects." (PMID 32280674, 2020). "Alfa-1-antitrypsin (SERPIN1A) and IL1RAP were elevated only in asthma patients with high LCI, as opposed to IgM, CD93 and CCL18 which were elevated also in asthma patients without small airway involvement." (PMID 35668386, 2022). "Therefore, our results showing that NK cells from allergic donors did not respond to CCL18 may suggest that efficient crosstalk between dendritic cells and NK cells may be disrupted in allergic patients, participating in the defect in the NK cell activation observed in asthma." (PMID 33918621, 2021).
esophageal squamous cell carcinoma (6 papers, 2020 to 2024). Esophageal squamous cell carcinoma (ESCC) is a type of esophageal carcinoma (EC) that can affect any part of the esophagus, but is usually located in the upper or middle third. "CCL18 upregulates the expression of HOTAIR, and the knockdown of HOTAIR alleviates the CCL18-induced invasiveness of Esophageal squamous cell carcinoma (ESCC) cells." (PMID 36997931, 2023). "In esophageal squamous cell carcinoma, CCL18 increases the expression of the hox transcript antisense intergenic RNA (HOTAIR)." (PMID 33114763, 2020). "HOTAIR can “sponge” miR-130a-5p to regulate ZEB1 and thus promoting malignant progression of esophageal squamous cell carcinoma, while HOTAIR is regulated by chemokine (C-C motif) ligand 18 (CCL18), which plays an important role in tumor progression and metastasis." (PMID 35093153, 2022).